CDIP1 (cell death inducing p53 target 1)
Synonyms: C16orf5; CDIP; LITAFL; I1
Tractability: Antibody: UniProt places it where antibodies can reach, with high confidence. PROTAC: ubiquitination databases record sites on it.
Gene: Protein-coding gene on chromosome 16 (4,510,619 to 4,538,828, reverse strand). Ensembl gene ENSG00000089486.
Subcellular location: Late endosome membrane; Lysosome membrane
Subcellular location (Human Protein Atlas): Centrosome; Nucleoplasm
Gene Ontology:
Molecular function: protein binding; zinc ion binding
Cellular component: centrosome; cytoplasmic side of late endosome membrane; cytoplasmic side of lysosomal membrane; late endosome membrane; lysosomal membrane; nucleoplasm; nucleus
Genetic constraint (gnomAD): Loss-of-function variants: 9 observed, 13.75 expected, observed/expected ratio (o/e) 0.65, 90% interval 0.39 to 1.14. The upper end of that interval is the gene's LOEUF score, 1.14, which puts it in group 5 of 6, group 1 being the genes least tolerant of losing a copy. Missense variants: 260 observed, 256.78 expected, observed/expected ratio (o/e) 1.01, 90% interval 0.91 to 1.12. Synonymous variants: 116 observed, 98.72 expected, observed/expected ratio (o/e) 1.17, 90% interval 1.01 to 1.37.
Homologues: Orthologues: chimpanzee CDIP1 (99% identical), macaque CDIP1 (99% identical), rabbit CDIP1 (98% identical), guinea pig CDIP1 (96% identical), dog CDIP1 (96% identical), pig CDIP1 (95% identical), mouse Cdip1 (94% identical), rat Cdip1 (94% identical), zebrafish cdip1 (63% identical), tropical clawed frog cdip1 (61% identical), Caenorhabditis elegans F16F9.1 (20% identical), Caenorhabditis elegans Y22D7AL.15 (19% identical), and 9 more. Paralogues in human: LITAF (26% identical).
Diseases named in the same sentence as CDIP1 in open-access papers:
CDIP1 is named in the same sentence as 13 diseases in open-access papers, as found by Europe PMC text mining. Sharing a sentence is not in itself a finding about the gene and the disease. The quoted sentences say what the papers report.
myocardial infarction (2 papers, 2021 to 2024). Gross necrosis of the myocardium, as a result of interruption of the blood supply to the area, as in coronary thrombosis. "Several studies indicated that the downregulation of Cdip1 improved angiogenesis and attenuated apoptosis after myocardial infarction." (PMID 39224379, 2024).
breast carcinoma (1 paper, 2024). "In this study, we first demonstrated that CDIP1 was upregulated after treatment with the anticancer drug adriamycin in human breast cancer MCF-7 cells but was degraded rapidly in the lysosomal pathway." (PMID 38928226, 2024).
cardiac hypertrophy (1 paper, 2025). "Additionally, our work corroborates the contribution of the miR-133b-3p/CDIP1 axis to cardiac hypertrophy." (PMID 39943804, 2025). "Therefore,CDIP1 is a target of miR-133b-3p involved in the regulation of cardiac hypertrophy." (PMID 39943804, 2025).
epilepsy (1 paper, 2021). A brain disorder characterized by episodes of abnormally increased neuronal discharge resulting in transient episodes of sensory or motor neurological dysfunction, or psychic dysfunction. "The human CDIP1 gene was first cloned as C16ORF5 near a region of chromosome 16 associated with a de novo translocation in a patient with epilepsy and mental retardation." (PMID 33503978, 2021).
ischemic heart disease (1 paper, 2023). "The CircNCX1/miR-133a-3p/CDIP1 axis could provide a potential approach to facilitate treatment decisions for ischemic heart disease." (PMID 36835653, 2023).
tumour (5 papers, 2018 to 2024). "Not surprisingly, CDIP1 also plays an important role in tumor cell apoptosis." (PMID 35042833, 2022).
cancer (3 papers, 2016 to 2022). A tumor composed of atypical neoplastic, often pleomorphic cells that invade other tissues. "Some of the high scoring BioChIP-seq enrichment sites included genes that have been implicated in cancer metastases (DDR1, BMP4, and SMAD6), and cell cycle and survival (CDIP1 and PPP2R5A)." (PMID 36207293, 2022). "Thus, ALG-2 could function as a proapoptotic protein by interacting with CDIP1 in response to intracellular Ca2+ mobilization in cancer cells expressing CDIP1." (PMID 33503978, 2021). "Therefore, CDIP1 would be a potential target for ALG-2 in cancer patients undergoing chemotherapy." (PMID 33503978, 2021).
heart (1 paper, 2025). "Moreover,CDIP1 is abundantly expressed in the heart and may significantly contribute to the development of heart pathologies." (PMID 39943804, 2025).
CDIP1 also shares sentences with these, for which no sentence is quoted: infection (3 papers); colorectal cancer (1); fungal infection (1); non-small cell lung carcinoma (1); Obesity (1).